RPGR (retinitis pigmentosa GTPase regulator)
Diseases named in the same sentence as RPGR in open-access papers (continued):
Sharing a sentence is not in itself a finding about the gene and the disease.
autosomal dominant retinitis pigmentosa (1 paper, 2020). Autosomal dominant retinitis pigmentosa (RP) is an autosomally dominant inherited retinal dystrophy leading to progressive loss of the photoreceptors and retinal pigment epithelium and resulting in blindness usually after several decades. "For patients with autosomal dominant retinitis pigmentosa (RP), the most frequently associated genes were RHO, RP1, and PRPF31; for X-linked and autosomal recessive forms of RP, the most frequently associated genes were RPGR and USH2A, respectively." (PMID 32423767, 2020).
Best vitelliform macular dystrophy (1 paper, 2019). Best vitelliform macular dystrophy (BVMD) is a genetic macular dystrophy characterized by loss of central visual acuity, metamorphopsia and a decrease in the Arden ratio secondary to an egg yolk-like lesion located in the foveal or parafoveal region. "In case 53 (a male), a pathogenic change in BEST1 explains the Best vitelliform macular dystrophy phenotype, however, a truncating variant in RPGR would also be expected to be causative." (PMID 30718709, 2019).
breast carcinoma (1 paper, 2023). "In addition, RPGR is one of the top driver oncogenes in breast cancer." (PMID 37427104, 2023).
bronchiectasis (1 paper, 2024). Segmental, irreversible dilation of the bronchial tree resulting in the accumulation of secretions which leads to obstruction. "Patients with RPGR variants have rarely also been noted to have recurrent sinus, ear, and lung infections with the development of bronchiectasis but not laterality defects, with RPGR playing a role in both respiratory cilia and photoreceptor cilia." (PMID 38891105, 2024).
fragile X syndrome (1 paper, 2022). A genetic syndrome caused by mutations in the FMR1 gene which is responsible for the expression of the fragile X mental retardation 1 protein. "High-prevalence yet technically challenging variant types, e.g. CNVs (copy-number variations) in spinal muscular atrophy, repeat expansions in the Fragile X syndrome and the highly repetitive and purine-rich ORF15 region in RPGR, were not included." (PMID 36535936, 2022).
glaucoma (1 paper, 2025). Increased pressure in the eyeball due to obstruction of the outflow of aqueous humor. "We found that the inhibitor of the Rho/ROCK pathway ripasudil, a clinically approved drug for the treatment of glaucoma, mediated benefits to the normal actin turnover and rescued the ciliary defects associated with RPGR loss." (PMID 41323795, 2025).
glioblastoma (1 paper, 2022). The most malignant astrocytic tumor (WHO grade IV). "For the remaining seven DEPCGs (ZWILCH, RPGR, ZNF460, ZNF528, QTRT2, C5orf15 and CNTRL), no previous functional associations were found with glioblastoma progression, despite a number of them being associated with other cancer types." (PMID 36497269, 2022).
Joubert syndrome (1 paper, 2022). Joubert syndrome (JS) is characterized by congenital malformation of the brainstem and agenesis or hypoplasia of the cerebellar vermis leading to an abnormal respiratory pattern, nystagmus, hypotonia, ataxia, and delay in achieving motor milestones. "Furthermore, we reveal that some Joubert syndrome mutations perturb INPP5E ciliary targeting, and clarify how each CLS works: (i) CLS4 recruits PDE6D, RPGR and ARL13B, (ii) CLS2-CLS3 regulate association to TULP3, ARL13B, and CEP164, and (iii) CLS1 and CLS4 cooperate in ATG16L1 binding." (PMID 36063381, 2022).
lung diseases (1 paper, 2026). "We demonstrate that MCCs with RPGR variants have reduced ciliation, shorter cilia, impaired cilia beat, or cilia beat incoordination, potentially resulting in compromised mucociliary clearance and lung diseases." (PMID 41915430, 2026).
lymph node metastasis (1 paper, 2023). "In summary, we constructed a lymph node metastasis-related predictive signature based on TEKT2 and RPGR expression to predict the prognosis, immune infiltration, and efficiency of individualized therapeutic agents." (PMID 37427104, 2023).
migraine (1 paper, 2021). "Three of the DE genes were DE after cold pressor test (i.e. C vs D) and were therefore not considered to be migraine genes (LUC7L3, SRC and RPGR)." (PMID 33859262, 2021).
Pearson syndrome (1 paper, 2024). Pearson syndrome is characterized by refractory sideroblastic anemia, vacuolization of bone marrow precursors and exocrine pancreatic dysfunction. "Remarkably, half of them (n = 4/8) were genotypically attributed to syndromic IRDs (syndromic: COH1, USH2A, RNU4ATAC; Pearson syndrome; isolated: RPGR, RP2, CACNA1F)." (PMID 39596324, 2024).
Pigmentary retinopathy (1 paper, 2025). An abnormality of the retina characterized by pigment deposition. "RPGR carriers were classified into four retinal phenotypes (normal, radial, focal pigmentary retinopathy, and male pattern phenotype) and compared against healthy controls." (PMID 40004550, 2025). "Notably, retinal remodelling was a common feature for RPGR carriers with focal pigmentary retinopathy and male pattern phenotypes demonstrating inner-retinal thickening when comparing carriers with healthy controls." (PMID 40004550, 2025).
retinal detachment (1 paper, 2024). An eye emergency condition which may lead to blindness if left untreated. "A similar widespread IS Rho mislocalization was also seen in a RPGR mutant dog model of X-linked RP, in a knockout mouse for the CC-localized and JBTS-associated Tmem138 membrane protein, and after experimental retinal detachment in cats." (PMID 38190419, 2024).
Senior-Løken syndrome (1 paper, 2010). "In addition, RPGR associates with NPHP proteins mutated in renal retinal syndromes, including SLSN and JBTS." (PMID 20664800, 2010).
Stroke (1 paper, 2024). Sudden impairment of blood flow to a part of the brain due to occlusion or rupture of an artery to the brain. "Microglia nodules compared to non-nodular (NA)WM in MS and in stroke shared only few communally upregulated DE genes (C1qB, RPGR, and SLC11A1), which are associated with involvement in activation of the classical complement pathway and in phagocytosis." (PMID 38396116, 2024).
X-linked disease (1 paper, 2023). X-linked form of disease. "The underrepresentation of variants detected in genes on the X chromosome might be explained by more extensive targeted testing of X-linked IRD genes such as RPGR (prior to smMIPs sequencing) in probands with X-linked diseases." (PMID 36819107, 2023).
retinopathy (10 papers, 2018 to 2025). "This study cohort, therefore, includes both affected male individuals as well as female carriers with clinical or electrophysiological features of retinopathy or retinal dysfunction in keeping with RPGR-associated IRD." (PMID 38219857, 2024). "To conclude, the clinical and genetic spectrum of RPGR-associated retinal disorder was first illustrated in a Japanese population, with a high proportion of novel variants." (PMID 31645972, 2019). "By identifying conserved phagolysosomal degradation defects across zebrafish and human cell lines, we highlight lysosomal reactivation as a therapeutic strategy for RPGR-related retinopathies." (PMID 41288322, 2025). "Several candidate genes associated with CQ/HCQ retinopathy were found with exome sequencing, including RP1L1, RPGR, RPE65, CACNA2D4, EYS, RP1, IMPG1 and ABCA4." (PMID 38548946, 2024). "In this study, several candidate susceptibility genes including RP1L1, RPGR, RPE65 and CCDC66 were identified to be associated with CQ/HCQ retinopathy via exome sequencing and genome-wide association study." (PMID 38548946, 2024). "Several candidate susceptibility genes including RP1L1, RPGR, RPE65 and CCDC66 were identified to be associated with CQ/HCQ retinopathy." (PMID 38548946, 2024). "Several candidate genes associated with CQ/HCQ retinopathy were found, including RP1L1, RPGR and RPE65, with a difference of affected percentage over 50% in mutation between the case and control groups." (PMID 38548946, 2024). "Similar reasons could be behind the phenotypic spectrum of RPGR-retinopathy." (PMID 33805381, 2021).
cancer (3 papers, 2021 to 2022). A tumor composed of atypical neoplastic, often pleomorphic cells that invade other tissues. "RPGR encodes the retinitis pigmentosa GTPase regulator, whose function in NPC and cancer is unknown." (PMID 34805186, 2021).
genetic diseases (3 papers, 2020 to 2024). "Since XLRP caused by mutations in the RPGR gene is among the most frequent genetic disorders of the retina and shows an early age of onset, treatment options are currently under development." (PMID 33182541, 2020).
tumor (1 paper, 2023). "RT-qPCR results revealed that the mRNA expression of TEKT2 and RPGR was significantly downregulated in tumor samples, especially in metastatic lymph node samples." (PMID 37427104, 2023).
RPGR also shares sentences with these, for which no sentence is quoted: deafness (2 papers); Leber congenital amaurosis 2 (2); retinoschisis (2); Alström syndrome (1); and recessive retinitis pigmentosa (1); autosomal recessive retinitis pigmentosa (1); Bardet-Biedl syndrome (1); Bietti crystalline dystrophy (1); blue cone monochromacy (1); chorioretinal degenerations (1); choroiditis (1); chronic granulomatous disease (1); corneal dystrophy (1); COVID-19 (1); cystic fibrosis (1); cystoid macular edema (1); familial hypercholesterolemia (1); glomerulonephritis (1); hemophilia A (1); infection (1); lung carcinoma (1); McLeod syndrome (1); Norrie disease (1); Nystagmus (1); ocular albinism (1); oculocutaneous albinism (1); polycystic kidneys (1); progressive external ophthalmoplegia (1); Pseudoxanthoma elasticum (1); retinitis (1).
A further 10 diseases each share a sentence with RPGR in 1 paper.